BCORL1 (BCL6 corepressor like 1)
Diseases named in the same sentence as BCORL1 in open-access papers:
BCORL1 is named in the same sentence as 50 diseases in open-access papers, as found by Europe PMC text mining. Sharing a sentence is not in itself a finding about the gene and the disease. The quoted sentences say what the papers report.
myeloid malignancies (7 papers, 2017 to 2026). "Some studies have demonstrated poor prognosis in patients with myeloid tumors with BCOR/BCORL1 mutations." (PMID 41262533, 2026). "BCOR/BCORL1 mutations are common in myeloid tumors, such as acute myeloid tumors, and detectable mutation types include small insertions and deletions, frameshift mutations, nonsense mutations, and splice site mutations." (PMID 41262533, 2026). "Somatic mutations in BCORL1 have been reported in myeloid malignancies." (PMID 28427458, 2017). "Here, we review a case series of pediatric and adolescent patients, with de novo AML/MDS, harboring BCOR/BCORL1 mutations, adding to the growing body of research investigating the role of BCOR and BCORL1 mutations in pediatric myeloid malignancies." (PMID 40805145, 2025). "Carriers of BCORL1 mutation, such as PIGA and BCOR, exhibit a lower risk of progressing to secondary myeloid neoplasms, and thus, this variant could represent a marker of immune selection without being a significant driver of myeloid malignancy." (PMID 36499545, 2022). "BCORL1 and JAK2 gene alterations have been demonstrated in various tumors including myeloid neoplasms." (PMID 34514557, 2021).
aplastic anemia (6 papers, 2019 to 2024). Anemia resulting from bone marrow failure (aplastic or hypoplastic bone marrow). "While the BCOR gene and its homolog BCORL1 are implicated in various hematologic malignancies and aplastic anemia, their association with allo-HSCT is rarely reported." (PMID 39408588, 2024). "Individuals with aplastic anemia (who carry oligo-clonal T-cell attacking their BM) presented with increased rate of BCOR and BCORL1 mutations." (PMID 37045808, 2023). "BCORL1 and ASXL1 mutations are mainly seen in hematologic malignancies and aplastic anemia." (PMID 38142265, 2024). "BCOR/BCORL1 mutations are common in aplastic anemia patients; their presence in LGLL without evidence of any other hematological disorders suggest that they may occur both in myeloid and lymphoid cells." (PMID 36358655, 2022).
acute myeloid leukemia (3 papers, 2022 to 2025). Acute myeloid leukemia (AML) is a group of neoplasms arising from precursor cells committed to the myeloid cell-line differentiation. "The significance of rare genetic alterations, such B-cell lymphoma-6 corepressor (BCOR) and B-cell lymphoma-6 corepressor-like protein 1 (BCORL1) mutations, in pediatric acute myeloid leukemias (AML) and myelodysplastic syndrome (MDS) is unknown." (PMID 40805145, 2025). "Poor-risk mutation carriers with AA have a 40% higher risk of clonal evolution to MDS or acute myeloid leukemia (AML) compared with patients with PIGA, BCOR, and BCORL1 mutations." (PMID 38646536, 2024).
hepatocellular carcinoma (3 papers, 2018 to 2021). A malignant tumor that arises from hepatocytes. "By targeting the BCL6 corepressor such as BCORL1, the migration and invasion of hepatocellular carcinoma (HCC) cells are restrained by miR-876-5p, which provides a new idea for the treatment of HCC." (PMID 33681362, 2021). "MiRNA-876-5p regulates tumor development by binding with BCL6 corepressor like 1 in hepatocellular carcinoma." (PMID 32440687, 2020). "For instance, by targeting BCL6 corepressor like BCORL1, the migration and invasion of hepatocellular carcinoma (HCC) cells are restrained by mir-876-5p, which provides a new idea for the treatment of HCC." (PMID 30186308, 2018).
leukemia (3 papers, 2023 to 2025). A malignant (clonal) hematologic disorder, involving hematopoietic stem cells and characterized by the presence of primitive or atypical myeloid or lymphoid cells in the bone marrow and the blood. "BCORL1 mutations were associated with MDS progression to leukemia, and BCORL1 VAF (HR = 1.025, p = 0.081) tended to be linked to the leukemic progression of MDS." (PMID 36982819, 2023). "BCOR and its homolog, B-cell lymphoma-6 corepressor-like protein 1 (BCORL1), are rarely altered (<2% incidence) in pediatric leukemias." (PMID 40805145, 2025). "Another CN-LOH region of interest was identified in sample S5, showing CN-LOH of Xq25–qter, involving four genes (STAG2, BCORL1, PHF6, and BRCC3) that have previously been implicated in different types of leukemias." (PMID 36831635, 2023).
myelodysplastic syndrome (3 papers, 2023 to 2025). A clonal hematopoietic disorder characterized by dysplasia and ineffective hematopoiesis in one or more of the hematopoietic cell lines. "The carriers of somatic PIGA and BCOR/BCORL1 mutations show a lower risk of AA transformation to myelodysplastic syndrome (MDS), whereas myeloid driver lesions such as DNMT3A and ASXL1 mutations characterize the group with a higher risk of malignancy." (PMID 38646536, 2024). "In patients with myelodysplastic syndrome (MDS) and myelodysplastic neoplasms (MPN), univariate analysis showed that BCORL1 had a significant impact on OS (p = 0.040); however, in multivariate analysis, there were no factors significantly associated with OS." (PMID 36799265, 2023).
developmental delay (2 papers, 2021 to 2022). "BCORL1 causes Shukla–Vernon syndrome (OMIM: 301029), an X-linked recessive neurodevelopmental disorder characterized by global developmental delay, variably impaired intellectual development, and behavioral abnormalities, including autism spectrum disorder and ADHD26." (PMID 35440622, 2022).
ependymoma (2 papers, 2020 to 2025). A WHO grade II, slow growing tumor of children and young adults, usually located intraventricularly. "Due to their scarcity and morphological features that mimic oligodendrogliomas and ependymomas, the diagnosis of CNS tumor with BCOR/BCORL1 fusion can be challenging, and misdiagnoses are not uncommon." (PMID 40724977, 2025).
glioblastoma (2 papers, 2021 to 2023). The most malignant astrocytic tumor (WHO grade IV). "Also,ZC3H18,SLIT2 CARF,GPATCH4,CAMK2D,BCORL1,ARHGAP4mutations were found in glioblastoma (T03)." (PMID 34430964, 2021).
glioma (2 papers, 2019 to 2020). A benign or malignant brain and spinal cord tumor that arises from glial cells (astrocytes, oligodendrocytes, ependymal cells). "Next-generation sequencing (NGS) of three cases identified mutations in a few genes known to be altered in low-grade gliomas, (e.g., BCOR, BCORL1, ERBB3, MYB, and ATM), but no recurrent mutations were seen." (PMID 31114608, 2019).
lymphoma (2 papers, 2020 to 2025). A malignant (clonal) proliferation of B- lymphocytes or T- lymphocytes which involves the lymph nodes, bone marrow and/or extranodal sites. "A notable example in our cohort was the identification of a BCORL1 mutation in a patient initially classified as lymphoma negative, prompting a re-evaluation of bone marrow aspirates and a revised diagnosis of marginal zone lymphoma." (PMID 40150070, 2025). "In particular, one patient initially classified as lymphoma negative was found to harbor a BCORL1 mutation (VAF 24.6%) through NGS." (PMID 40150070, 2025).
Myelodysplasia (2 papers, 2024 to 2025). Clonal hematopoietic stem cell disorders characterized by dysplasia (ineffective production) in one or more hematopoietic cell lineages, leading to anemia and cytopenia. "Eight myelodysplasia-associated somatic variants in the BCOR/BCORL1, DNMT3A, ASXL1, CUX1, and ETV6 genes were found in 7 patients (5 AA and 2 MDS-h patients, 17%); neither AA patient had evidence of myelodysplasia at the time of analysis." (PMID 41188636, 2025).
ossifying fibromyxoid tumor (2 papers, 2020). A rare soft tissue tumor of uncertain lineage characterized by the presence of neoplastic spindle to round cells forming cords in a fibromyxoid stroma. "A fusion involving CREBBP with BCORL1 has been described in ossifying fibromyxoid tumors, with a similar breakpoint region to that seen in our case, though with a distinct predicted fusion transcript that preserves the HAT domain of CREBBP." (PMID 32493417, 2020).
brain Tumors (1 paper, 2024). "Besides, five additional inputs were found after searching for alterations in BCOR, BCORL1, EP300, TRAP1, CREBBP, and L3MBTL2 in the repository of 23 published studies on neuroepithelial brain Tumors including 7207 samples of 6761 patients." (PMID 38637838, 2024).
chronic myelomonocytic leukemia (1 paper, 2021). A myelodysplastic/myeloproliferative neoplasm which is characterized by persistent monocytosis, absence of a Philadelphia chromosome and BCR/ABL fusion gene, fewer than 20 percent blasts in the bone marrow and blood, myelodysplasia, and absence of PDGFRA or PDGFRB rearrangement. "BCOR and BCORL1 proteins function as components of PRC1.1, a noncanonical PRC1, and are frequent targets of somatic mutations in AML, sAML, MDS, and chronic myelomonocytic leukemia (CMML)." (PMID 33799787, 2021).
diffuse large B-cell lymphoma (1 paper, 2021). "However, frequent mutations in some subunits, such as MGA and BCOR/BCORL1, as well as generally high mutation rates in cancers such as diffuse large B-cell lymphoma (DLBCL) and cholangiocarcinoma of the bile duct (CHOL) point to specific roles for Polycomb subunits in tumor suppression." (PMID 34617019, 2021).
diffuse midline glioma (1 paper, 2021). A diffuse glioma that arises from the midline structures of the central nervous system. "BCORL1 gene was mutated in thalamic diffuse midline glioma in our cohort and its expression is normally elevated within the ventral thalamus, claustrum, and cingulum bundle." (PMID 34257334, 2021).
learning disability (1 paper, 2017). A group of disorders that affect a person's ability to learn or process specific types of information which is in contrast to his/her apparent level of intellect. "Although this variant is very rare and not present in ExAC, the evidence supporting BCORL1 to be a causative gene for learning disability was limited;35 many of the proposed genes for X-linked learning disability have recently been challenged in light of data from large exome sequencing data sets." (PMID 28327575, 2017).
medulloblastoma (1 paper, 2021). A malignant, invasive embryonal neoplasm arising from the cerebellum. "Additionally, BCORL1 has been shown in medulloblastoma, retinoblastoma, and uterine sarcoma and might potentially be a pathogenic gene in the development of FDC/FRC." (PMID 34514557, 2021).
metastatic tumours (1 paper, 2020). "Other genes, such as BCORL1 (OVA_003), CASP3 (OVA_047), CHD2 (OVA_013), FAT3 (OVA_365) and LZTR1 (OVA_378), were heterogeneous, having differing clonality in the primary versus the metastatic tumours." (PMID 32099096, 2020).
microcephaly (1 paper, 2022). A congenital or acquired developmental disorder in which the circumference of the head is smaller than normal for the person's age and sex. "The syndromes or intellectual developmental disorders caused by variants in DIAPH1, AFF2, BCORL1 and BRWD3 are occasionally with abnormalities of cranium, such as microcephaly or macrocephaly tall forehead." (PMID 36118902, 2022).
peripheral artery disease (1 paper, 2024). "However, there is a documented case of a patient with a BCORL1 mutation, acquired or selected after HSCT, coinciding with the onset of severe peripheral artery disease." (PMID 39408588, 2024).
Shukla-Vernon syndrome (1 paper, 2021). "This is the second report of Shukla-Vernon syndrome with a novel missense variant in the BCORL1 gene." (PMID 33810051, 2021).
thrombosis (1 paper, 2025). "Age greater than 60 years, the presence of the cardiovascular risk factors, mutation for thrombosis (DNMT3A, ASXL1, or BCOR/BCORL1), and previous thrombosis made part of this score." (PMID 41153823, 2025).
tumor (19 papers, 2007 to 2025). "Instead, the tumor showed CREBBP::BCORL1 fusion and pathogenic mutations in BCOR and CREBBP, along with a DNA methylation profile matching the “CNS tumor with EP300:BCOR(L1) fusion” methylation class." (PMID 38216991, 2024). "The tumor mutation load showed BCL6 corepressor like 1 (BCORL1) and a-raf proto-oncogene (ARAF) have the highest copy number amplification, whereas lysine demethylase 6A (KDM6A) and RNA binding motif protein 10 (RBM10) showed the highest copy number deletion." (PMID 33629637, 2021). "BCORL1 is involved in tumor progression and respective mutations occur in HGGs and LGGs." (PMID 33639927, 2021). "Central nervous system (CNS) tumor with BCL6 corepressor gene BCOR/BCORL1 fusion is an extremely rare tumor entity, with fewer than 40 cases reported." (PMID 40724977, 2025). "Molecular tumor testing revealed pathogenic mutations with low VAF in KRAS, ARID1A, BCORL1, and PRKDC." (PMID 37966258, 2023). "BCOR/BCORL1 mutations are found in an array of cancers, and inactivating BCOR mutations have been identified in various hematological, epithelial and central nervous system (CNS) neoplasms." (PMID 34617019, 2021). "The BCORL1-fusion tumor was interpreted by the DKFZ classifier as a ‘no match,’ although it was also classified as CNS HGNET-BCOR with a low score (0.44)." (PMID 30514397, 2018). "In view of the limited evidence on therapies for this extremely rare tumor that matched the methylation class of CNS tumors with BCOR/BCORL1 fusion without a detectable fusion, we reasoned that radiation therapy was warranted given the high proliferative activity." (PMID 40724977, 2025). "As a result, in the initial stages of anti-androgen drug resistance there is decreased inflammatory response but down regulation of tumor suppressor targets of miR-146a, BCORL1 and RNASEL, which may not be detected in fully developed CRPC." (PMID 24387052, 2014).
cancer (8 papers, 2007 to 2025). A tumor composed of atypical neoplastic, often pleomorphic cells that invade other tissues. "We found telomere maintaining genes (TERF2, CTC1, and ACD), genes involved in zinc homeostasis (MTF1 and SLC30A9), transcription elongation factor complex components (ICE1, ICE2, ELL), and BCL6 corepressors (BCOR, BCORL1) uniquely invoked in TNBC cancers." (PMID 40700427, 2025). "In the second family in which MPT21 and two relatives were tested, we found four LP variants (BPIF1, BCORL1, ROPN1, and PRSS3) and four other cancer-related genes (TUBB2B, CFAP54, PSG2, and SIRPB1)." (PMID 39408606, 2024). "Variants in four genes (ROPN1, PRSS3, BPIFB1, and BCORL1) were detected in all individuals from Family 2, while four (TUBB2B, CAFAP54, PSG2, and SIRPB1) were exclusive of the MPT21 index case and her relative with cancer (MPT21.2)." (PMID 39408606, 2024). "Nonsynonymous mutations in four cancer-associated genes, CTNNA2 (11.1% vs. 5.8%; log10 p-value = −0.6), FLG (8.9% vs. 4.3%; log10 p-value = −0.6), GNAS (4.4% vs. 1.4%; log10 p-value = −0.5), and BCORL1 (17.0% vs. 11.6%; log10 p-value = −0.5), were more abundant in the case group." (PMID 32566745, 2020).
CNS tumors (4 papers, 2023 to 2025). "We present a case of a 37-year-old woman with a midline CNS tumor with BCOR/BCORL1 fusion, harboring a pathogenic BCOR c.626del (p.S209Cfs*7) (Exon 4) variant, who was successfully treated with definitive radiation therapy and adjuvant temozolomide." (PMID 40724977, 2025). "As we cultivate our understanding of CNS tumors with BCOR/BCORL1 fusions, the management for these patients will also continue evolve." (PMID 40724977, 2025). "Even rarer are CNS tumors that match to the methylation class of CNS tumors with BCOR/BCORL1 fusion, but lack fusions and instead harbor truncating small nucleotide variants in BCOR." (PMID 40724977, 2025). "Temozolomide was also selected for its efficacy in CNS tumors with BCOR/BCORL1 fusion and its favorable toxicity profile." (PMID 40724977, 2025). "Interestingly, the DNA methylation classification provides a specific MC for BCOR/BCORL1-fused CNS tumors, distinct from the BCOR-ITD CNS tumors." (PMID 39409964, 2024). "In addition, other CNS tumors harboring a BCOR/BCORL1 fusion, which are defined by a distinct DNA-methylation profile, have been recently identified in the literature but clinical, radiological and histopathological data remain scarce." (PMID 36782314, 2023). "Two CNS tumors with fusions between CREBBP, or its paralog EP300, and BCORL1, and approximately twenty CNS tumors with CREBBP/EP300::BCOR fusions have been reported to date." (PMID 38216991, 2024). "This case adds to the limited but growing body of evidence supporting the use of radiation and temozolomide in treating tumors matching the methylation class of CNS tumors with BCOR/BCORL1 fusion without a detectable fusion." (PMID 40724977, 2025). "The nature of a single case may not reflect the broader population of CNS tumors with BCOR/BCORL1 fusions in their entirety or those tumors matching to the same methylation class." (PMID 40724977, 2025).
hematologic malignancies (2 papers, 2020 to 2022). "In contrast, loss-of-function mutations in PRC genes, such as EZH2, EED, SUZ12, BCOR, and BCORL1, have been found in various hematological malignancies, suggesting their tumor suppressor functions." (PMID 33374737, 2020). "Among them, PRC 1.1, comprising PCGF1, RING1A/B, BCOR or BCORL1, and KDM2B, is of particular interest because of its distinct functions in hematopoietic stem cells and hematologic malignancies." (PMID 33374737, 2020).
neurodevelopmental disorder (2 papers, 2021 to 2022). A behavioral and cognitive disorder with onset during the developmental period that involves impaired or aberrant development of intellectual, motor, or social functions. "Accordingly, we attributed the Chiari malformation to the variant in KDM5B whereas the one in BCORL1 was presumably responsible for the mild neurodevelopmental disorder of both kids, as reported in Shukla–Vernon syndrome (#301029)." (PMID 33337535, 2021).
BCORL1 also shares sentences with these, for which no sentence is quoted: adenosarcoma (2 papers); pancreatic cancer (2); autism spectrum disorder (1); breast carcinoma (1); colon adenocarcinoma (1); endometrial cancer (1); fibromyxoid tumor (1); glioneuronal tumors (1); liver cancer (1); lung carcinoma (1); male breast carcinoma (1); marginal zone lymphoma (1); neuroepithelial tumor (1); oligodendroglioma (1); ovarian carcinoma (1); premature ovarian failure (1); prostate carcinoma (1); retinoblastoma (1); teratospermia (1); uterine adenosarcoma (1); uterine sarcoma (1).